METTL3 (methyltransferase 3, N6-adenosine-methyltransferase complex catalytic subunit)
Diseases named in the same sentence as METTL3 in open-access papers (continued):
Sharing a sentence is not in itself a finding about the gene and the disease.
tumor (continued). "To summarize, METTL3 plays a tumor promoting role in PCa progression and targeted therapy resistance at least by catalyzing some oncogenes (c-Myc) and core component of multiple signaling pathways including WNT signaling (CTNNB1), Hedgehog signaling (Gli), MAPK signaling (HRAS, MEK2)." (PMID 39268470, 2024). "Furthermore, co-immunoprecipitation studies in tumor cells have demonstrated that the binding affinity of METTL3 for METTL14 is significantly lower than that of METTL14 for METTL3." (PMID 38965238, 2024). "Cell experiments were performed to assess the effect of METTL3 interference on tumour cells." (PMID 38429907, 2024). "The GEPIA results showed that METTL3 was expressed at lower levels in tumor tissues." (PMID 39497721, 2024). "Likewise, the researchers confirmed that silencing METTL3 through knockdown was shown to inhibit tumor growth in mouse models." (PMID 38398118, 2024). "Moreover, by analysing GC cells isolated from SGC7901 mouse gastric graft tumour models, we also found that METTL3 knockdown had a similar effect." (PMID 38616702, 2024). "Consequently, targeting METTL3 with an enzymatic inhibitor can achieve a synergistic immunotherapeutic effect, targeting both the tumour cells and enhancing the vigor of T‐cell responses." (PMID 39568154, 2024). "METTL3 expression is higher in many tumor tissues than in normal tissues." (PMID 38166703, 2024). "Overall, in the clinical treatment of BCa, targeting METTL3 could present novel therapeutic strategies to overcome chemotherapy and immunotherapy resistance driven by tumor angiogenesis, thereby improving the clinical outcomes of patients." (PMID 39295872, 2024). "Additionally, METTL3 is known to augment the immunosuppressive abilities of tumor-infiltrating myeloid cells." (PMID 38902779, 2024). "The results indicated that METTL3 was generally expressed at lower levels in tumor tissues." (PMID 39497721, 2024). "A high level of histone lactylation in tumor-infiltrating myeloid cells induces METTL3 expression and m6A modification of Jak1 mRNA, which leads to the protein translation of Jak1 and the stimulation of downstream STAT3 signal that enhances myeloid immunosuppressive functions." (PMID 38200523, 2024). "METTL3 knockdown inhibited cell proliferation, glycolysis, and tumor growth." (PMID 38721006, 2024). "METTL3-induced chemoresistance has been detected in several tumors, suggesting that functional inhibition of METTL3 may restore tumor chemosensitivity." (PMID 38166703, 2024). "Early on, a study demonstrated that METTL3 or METTL14 might be a tumor suppressor for GSCs since knockdown of METTL3 or METTL14 expression by shRNA increased GSC growth and self-renewal." (PMID 38398118, 2024). "In addition, lactylation also mediates METTL3 expression to promote immunosuppression of tumor-infiltrating myeloid cells, further emphasizing the interaction between lactylation and m6A modification." (PMID 38297099, 2024). "miR-33a affects tumor proliferation processes by targeting METTL3 mRNA." (PMID 39473440, 2024). "Besides, platelet derived growth factor (PDGF) signaling can induce METTL3, decrease the tumor-suppressive Optineurin Gene (OPTN) protein levels and promote GSC proliferation and self-renewal." (PMID 38711100, 2024). "On the other hand, METTL3 has also been demonstrated as a tumor suppressor in CRC." (PMID 39136000, 2024). "For instance, in addition to its direct effects on ECs, VSMCs, and HSCs, METTL3 may also influence angiogenesis through its interaction with tumor surroundings." (PMID 39834386, 2024). "Depleting the macrophage METTL3-YTHDF1 axis promotes tumor growth and metastasis." (PMID 39133578, 2024). "Our findings suggest that dysregulation of METTL3-mediated m6A modification may impact LUAD progression by promoting tumor angiogenesis." (PMID 39497721, 2024). "Furthermore, we found that PX‐478 suppressed METTL3 expression in mouse gastric graft tumour models and in the gastric mucosa of mice with PHT." (PMID 38616702, 2024).
tumor (continued). "As a homolog of METTL3, METTL14 shares some similarities, but METTL14 is downregulated in HCC, is closely associated with tumor metastasis, and plays a regulatory role in the process of HCC tumor metastasis." (PMID 39229278, 2024). "It is worth noting that we also observed a significant reduction in tumor migration upon inhibiting METTL3, suggesting that therapeutic strategies targeting METTL3 may be an effective approach for treating CRPM." (PMID 38605400, 2024). "METTL3’s role in modulating immune cell function and its impact on the tumor microenvironment could uncover new avenues for immunotherapy." (PMID 39834386, 2024). "Similarly, in seminomas, tumor sensitivity to cisplatin was improved by inhibiting METTL3 and autophagy, improving therapeutic efficacy." (PMID 39033180, 2024). "Collectively, these results showed that METTL3 promoted LUAD tumour growth in vitro and in vivo." (PMID 39095708, 2024). "METTL3 inhibition suppresses lymphatic vessel growth in both corneal and tumor models." (PMID 39372388, 2024). "METTL3 knockdown suppressed cell viability, angiogenesis, tumor growth, and liver metastasis." (PMID 38721006, 2024). "In addition, PDX tumor models were injected with METTL3 siRNA to assess the therapeutic effect of METTL3." (PMID 39136000, 2024). "Additionally, m6A modification mediated by Mettl3 in T cells regulates the migration of T cells in an acidic tumor microenvironment." (PMID 39372415, 2024). "In summary, these results suggest that METTL3 inhibition can induce potent anti‐tumour immunity." (PMID 39568154, 2024). "In addition, the knockout (KO) of m6A methyltransferase METTL3 or the use of inhibitor can also enrich immune pathway in tumour cells and upregulate the expression of antigen presentation, thereby enhancing the effect of ICB treatment." (PMID 39568154, 2024). "To explore the effect of METTL3 on tumor migration, we performed transwell assays." (PMID 39497721, 2024). "Similarly, in GC, METTL3 promotes tumor angiogenesis through the ADAM metallopeptidase with thrombospondin type 1 motif 9 (ADAMTS9)-mediated PI3K/AKT pathway." (PMID 39098905, 2024). "Recently, methyltransferase-like 3 (METTL3)-mediated N6-methyladenosine (m6A) modification has been demonstrated to play an important role in the occurrence and progression of various cancers and a tumour suppressor role in TC." (PMID 38993572, 2024). "A high level of METTL3 promotes the formation of an immunosuppressive tumour microenvironment." (PMID 39735605, 2024). "Importantly, elevated levels of METTL3 within tumour microenvironments significantly correlated with the advanced tumour stage, poor overall survival (OS), and poor disease‐free survival (DFS) in patients with CC." (PMID 38332508, 2024). "In addition, we found that the xenograft tumours formed by METTL3-overexpressing cells were both larger in size and heavier in size than those formed by control cells as well." (PMID 39095708, 2024). "METTL3, a common methyltransferase, is upregulated in various tumors to regulate tumor progression." (PMID 39349442, 2024). "METTL3 knockdown attenuates corneal sutures‐induced lymphangiogenesis and intratumoral lymphangiogenesis initiated by subcutaneous grafts, consequently restraining corneal neovascularization, tumor growth, and tumor neovascularization." (PMID 39372388, 2024). "As expected, either Mettl3–lecKO or bevacizumab administration inhibited tumor growth." (PMID 39372388, 2024). "In addition, LA accumulation in tumor cells can also improve immunosuppressive ability by promoting the expression of METTL3." (PMID 39033180, 2024). "When METTL3 is knocked out in NK cells, the tumor infiltration and the ability to secrete immune factors such as GzmB and INF-γ are significantly decreased, cytotoxicity is markedly reduced, and an increase in expression levels of the inhibitory receptor TIGIT is observed in the TME." (PMID 39372415, 2024).
tumor (continued). "For example, overexpression of METTL3 may enhance the sensitivity of tumor cells to certain chemotherapy drugs, while high expression of ALKBH5 may lead to resistance." (PMID 39473440, 2024). "STM2457 is the first bioavailable small-molecule inhibitor of METTL3 (a regulator of m6A methyltransferase) that affects the inhibition of catalytic activity and upregulation of METTL3 increasing PD-L1 and reduction of tumor progression in NSCLC (non-small-cell lung cancer)." (PMID 38543112, 2024). "Our in vivo experiments revealed that the administration of STM2457 significantly abrogated RCC progression by reducing xenograft tumor growth, suggesting that METTL3 may serve as a potential target for RCC therapy." (PMID 38233403, 2024). "As the main force in the immune system's tumour‐killing activity, CD8+ T cells may play a crucial role in enhancing the tumour‐killing effect with METTL3 inhibition." (PMID 39568154, 2024). "Additionally, Mettl3 can regulate tumor cell sensitivity to chemotherapy and immunotherapy, making it a potential target for cancer therapy." (PMID 37007040, 2023). "Additionally, METTL3 knockdown inhibited PDAC aggressive tumor phenotypes through, at least in part, by weakening DDX23 mRNA m6A modification." (PMID 36977668, 2023). "Consistent with TCGA data analysis, METTL3 was highly expressed in tumor tissues." (PMID 36697384, 2023). "An in vivo study further confirmed that knockdown of METTL3 could decrease miR-146b expression, leading to an increase in TAMs and ultimately promoting tumor progression." (PMID 37402945, 2023). "Similarly, immunohistochemical staining proved that tumor tissues had higher METTL3 protein expression." (PMID 37244946, 2023). "Ten host and one tumor cell clusters were identified in WT and Mettl3-cKO mice." (PMID 37932814, 2023). "Further functional studies showed that miR221/222 directly targeted and inhibited phosphate and tension homology (Pten) expression and promoted tumour progression, and METTL3 plays a cancerous role in BC by positively regulating pri-miR221/222 processes in an m6A-dependent way." (PMID 37284313, 2023). "Posttranslational modification of METTL3 also plays a key role in tumor invasion and metastasis." (PMID 39872957, 2023). "Additionally, miR-186 has been identified as a direct target of METTL3, with ectopic overexpression of miR-186 leading to a significant decrease in aggressive tumor phenotypes in HB." (PMID 37915034, 2023). "However, our results illustrated that chemotherapy-mediated depletion of METTL3 plays a significant unprotective role in tumour progression and drug tolerance." (PMID 36765397, 2023). "METTL3/14 can act as either a tumor promoter or a tumor suppressor in GI cancers." (PMID 38187373, 2023). "In the TIME, METTL3 expression is inhibited in infiltrating NK cells by tumor derived TGF-β." (PMID 37015927, 2023). "In addition, the manipulation of ubiquitination-mediated degradation of multiple tumor metastasis-related genes by METTL3 to regulate tumor cell migration and invasion has attracted attention." (PMID 37996892, 2023). "In addition, METTL3 enhances the immunosuppressive function of tumor-infiltrating myeloid cells (TIMs) through the Jak1/STAT3 pathway by promoting Jak1 translation through the m6A-YTHDF1 axis." (PMID 37485079, 2023). "Besides, CAPRIN1 knockdown inhibits ESCC cell proliferation and tumour growth and decreased the expression of METTL3 and WTAP." (PMID 36855123, 2023). "Although METTL3 promotes the proliferation of most tumor cells, there are always exceptions." (PMID 37559091, 2023). "METTL3 expression in tumour xenografts was evaluated by IHC." (PMID 36932427, 2023). "Depletion of METTL3 in macrophages enhances tumorigenesis and tumor progression by facilitating the development of an immunosuppressive microenvironment through the upregulation of infiltration levels of M1- and M2-macrophages as well as regulatory T cells (Tregs)." (PMID 37606975, 2023).
tumor (continued). "METTL3-knockdown M2 macrophages promoted tumor growth in tumor-bearing C57BL/6 mice." (PMID 37402945, 2023). "The role of METTL3 in the immune microenvironment and immune infiltration remains to be further investigated, but there is no doubt that targeting METTL3 therapy is a novel means to overcome the challenge of tumor immune escape." (PMID 37996892, 2023). "Early time, METTL3 up-regulated in tumor tissues was negatively related with patients’ DFS and OS." (PMID 37598390, 2023). "Taken together, those reports demonstrated that METTL3 may serve as a potential therapeutic target for tumor immunotherapy in the future." (PMID 39872957, 2023). "These contradictory results suggest the complex functions of METTL3 in tumor microenvironment." (PMID 37151889, 2023). "Knocking down Mettl3 in macrophages promoted MC38 tumor growth." (PMID 37402945, 2023). "The expression of METTL3 in the tumour xenografts was also evaluated by IHC." (PMID 36932427, 2023). "Finally, subcutaneous tumor experiments conducted in nude mice also confirmed that METTL3 regulated CRC progression through STAG3 in vivo." (PMID 37828232, 2023). "The recent identification of a selective inhibitor of METTL3 catalytic activity that dramatically decreases tumor growth in mouse AML models suggests that m6A methylation by METTL3 could serve as a promising therapeutic target for cancer treatment." (PMID 37589705, 2023). "Moreover, FTO and ALKBH5 function as tumor suppressors by inhibiting METTL3 while promoting METTL14 expression." (PMID 37580808, 2023). "Furthermore, compared with tumor-bearing WT mice, Mettl3-cKO mice indicated a significantly higher secretion of CCL2 in peritoneal lavage and peripheral blood and CXCL2 in only peritoneal lavage but not in peripheral blood." (PMID 37932814, 2023). "In addition, METTL3 ubiquitination level was reduced in tumor tissues which highly expressed USP13 compared to adjacent normal tissues." (PMID 37151889, 2023). "Knockdown of METTL3 or circUHRF2 suppressed circUHRF2 expression in tumor tissues." (PMID 37370759, 2023). "Different studies have indicated that METTL3/14 may play opposing roles within the same type of tumor." (PMID 38187373, 2023). "Another study also revealed that METTL3 promotes tumor progression by maintaining SOX2 expression." (PMID 37151889, 2023). "In addition, CD8+PD-1+ T cells were upregulated in our Mettl3LKI mouse tumor, implying that METTL3 suppressed T cell effector function and promoted T cell exhaustion." (PMID 37586322, 2023). "Another study demonstrates that depletion of METTL3 or METTL14 could increase the sensitivity of anti-PD-1 therapy by supporting the function of cytotoxic tumor‐infiltrating CD8 T cells." (PMID 37965577, 2023). "The dual regulatory function of Mettl3 in CC poses an intriguing scientific inquiry, whether it arises from the heterogeneity of tumor cells, the distinctive biological properties of Mettl3, or other underlying factors." (PMID 37007040, 2023). "The increased secretion of CCL2 and CXCL2 may have accounted for the enhanced migration of MDSCs in the peritoneal cavity of tumor-bearing METTL3-cKO mice." (PMID 37932814, 2023). "In addition, several studies have reported the potential tumor-promoting or tumor-suppressing effects of m6A methylation-related factors such as METTL3, METTL14 and FTO in PCa." (PMID 37033963, 2023). "Furthermore, it has been shown that METTL3/14 modulates immune cell infiltration in an m6A-dependent manner in TIME (Tumor immune microenvironment), thereby altering the response of cancer cells to ICIs (Immune checkpoint inhibitors)." (PMID 38187373, 2023). "It should be noticed that METTL3 is found to play the tumor-suppressive function in papillary TC." (PMID 37915103, 2023). "Furthermore, METTL3 directly regulates the expression of cell cycle proteins and affects tumor growth." (PMID 37996892, 2023).
tumor (continued). "Therefore, we believe that Erianin induces an increase in the m6A methylation modification of multiple genes by promoting the expression of m6A methylation transferase METTL3 in tumor cells." (PMID 36860916, 2023). "With further research, METTL3 may become a molecular marker for tumor diagnosis as well as a treatment target." (PMID 37996892, 2023). "Histological staining of tumor sections with hematoxylin and eosin (H&E) showed that the tumor lesion area in mouse limbs was greatly reduced by knockdown of METTL3 and YTHDF1 along with reduced tartrate resistant acid phosphatase (TRAP), indicative of clear decreases in osteoclast activity." (PMID 36923927, 2023). "Finally, we performed morphological examination on the collected tumor samples and found that si-METTL3 inhibited proliferation and promoted apoptosis in tumor tissue." (PMID 37088992, 2023). "The overexpression of RBM14 inhibited the anti-tumor effects of sh-METTL3 in vitro and in vivo." (PMID 36835633, 2023). "Notably, the results we have summarized show that METTL14 from tumor cells has a completely opposite effect of METTL3." (PMID 37152066, 2023). "The main enzyme of m6A modification, METTL3, could facilitate tumor progression by depositing m6A modification on key transcripts." (PMID 37965577, 2023). "Notably, we observed that METTL3 silence effectively suppressed tumor growth in both the subcutaneous parent cell line and GEM-resistant cell line transplantation models in nude mice." (PMID 36977668, 2023). "METTL3, a typical m6A methyltransferase, suppresses tumor immune surveillance in breast cancer." (PMID 37485079, 2023). "Tumor cell proliferation and survival were significantly suppressed after METTL3 deletion." (PMID 36609396, 2023). "In addition, we measured the METTL3 expression in a GC cohort with 40 paired tumor tissues and adjacent normal tissues." (PMID 37999596, 2023). "Additionally, METTL3 inhibition led to the increased expression of PD-L1 on the surface of tumor cells, suggesting the potential to enhance therapies targeting the PD1/PD-L1 ICI." (PMID 38072988, 2023). "METTL3 relies on m6A modification to affect tumor cell drug resistance at multiple levels, including expression of anticancer drug targets and multidrug transporter proteins, classical signaling pathway switches, cellular antioxidant effects, DNA damage repair, cellular autophagy, and apoptosis." (PMID 37996892, 2023). "In addition, METTL3 regulates the ubiquitination of metastasis-related target genes, thereby promoting tumor metastasis." (PMID 37996892, 2023). "METTL3 directly modulates the cell cycle to promote tumor cell proliferation, which undoubtedly provides a new perspective in our understanding of malignant tumor proliferation." (PMID 37996892, 2023). "In endometrial cancer, reduced METTL3 expression leads to a decrease in m6A modification on PHLPP2 mRNA, resulting in attenuated YTHDF1-mediated translation of PHLPP2, which in turn caused de-repression of the AKT pathway and promotes tumor progression." (PMID 36830614, 2023). "Simvastatin significantly abolished the tumor-promoting effect of METTL3." (PMID 37586322, 2023). "As the key catalytic subunit mediating m6A modification, METTL3 has been reported to be expressed aberrantly in various tumors, including hematopoietic malignancies and solid tumors, and plays vital roles in tumor progression as an m6A regulator, either as a tumor suppressor or an oncogene." (PMID 37915103, 2023).